FBXO5 (F-box protein 5)
Description:
Regulator of APC activity during mitotic and meiotic cell cycle. During mitotic cell cycle plays a role as both substrate and inhibitor of APC-FZR1 complex. During G1 phase, plays a role as substrate of APC-FZR1 complex E3 ligase. Then switches as an inhibitor of APC-FZR1 complex during S and G2 leading to cell-cycle commitment. As APC inhibitor, prevents the degradation of APC substrates at multiple levels: by interacting with APC and blocking access of APC substrates to the D-box coreceptor, formed by FZR1 and ANAPC10; by suppressing ubiquitin ligation and chain elongation by APC by preventing the UBE2C and UBE2S activities. Plays a role in genome integrity preservation by coordinating DNA replication with mitosis through APC inhibition in interphase to stabilize CCNA2 and GMNN in order to promote mitosis and prevent rereplication and DNA damage-induced cellular senescence. During oocyte maturation, plays a role in meiosis through inactivation of APC-FZR1 complex. Inhibits APC through RPS6KA2 interaction that increases FBXO5 affiniy for CDC20 leading to the metaphase arrest of the second meiotic division before fertilization (By similarity). Controls entry into the first meiotic division through inactivation of APC-FZR1 complex (By similarity). Promotes migration and osteogenic differentiation of mesenchymal stem cells.
Synonyms: EMI1; FBX5; Fbxo31
Tractability: PROTAC: UniProt records ubiquitination sites on it; ubiquitination databases record sites on it.
Gene: Protein-coding gene on chromosome 6 (152,970,519 to 152,983,579, reverse strand). Ensembl gene ENSG00000112029.
Subcellular location: Nucleus; Cytoplasm; Cytoplasm, cytoskeleton, spindle
Subcellular location (Human Protein Atlas): Nucleoplasm
Pathways (Reactome):
Cell Cycle: G1/S-Specific Transcription; Mitotic Metaphase/Anaphase Transition; Phosphorylation of Emi1; Regulation of APC/C activators between G1/S and early anaphase; SCF-beta-TrCP mediated degradation of Emi1
Gene Ontology:
Molecular function: anaphase-promoting complex binding; molecular function inhibitor activity; protein binding; protein kinase binding; ubiquitin ligase inhibitor activity
Biological process: DNA damage response; negative regulation of cellular senescence; negative regulation of DNA endoreduplication; negative regulation of mitotic metaphase/anaphase transition; negative regulation of ubiquitin protein ligase activity; negative regulation of ubiquitin-protein transferase activity; positive regulation of biomineral tissue development; positive regulation of cell population proliferation; positive regulation of G2/M transition of mitotic cell cycle; positive regulation of mesenchymal stem cell migration; positive regulation of osteoblast differentiation; regulation of DNA replication; negative regulation of meiotic nuclear division; regulation of mitotic cell cycle; regulation of mitotic nuclear division; SCF-dependent proteasomal ubiquitin-dependent protein catabolic process; negative regulation of cell cycle process; protein ubiquitination
Cellular component: cytoplasm; nucleoplasm; nucleus; spindle; cytosol; meiotic spindle; SCF ubiquitin ligase complex
Genetic constraint (gnomAD): Loss-of-function variants: 5 observed, 29.03 expected, observed/expected ratio (o/e) 0.17, 90% interval 0.089 to 0.36. The upper end of that interval is the gene's LOEUF score, 0.36, which puts it in group 1 of 6, group 1 being the genes least tolerant of losing a copy. Missense variants: 459 observed, 497.45 expected, observed/expected ratio (o/e) 0.92, 90% interval 0.85 to 1. Synonymous variants: 191 observed, 181.93 expected, observed/expected ratio (o/e) 1.05, 90% interval 0.93 to 1.18.
Homologues: Orthologues: chimpanzee FBXO5 (99% identical), macaque FBXO5 (98% identical), rabbit FBXO5 (85% identical), dog FBXO5 (81% identical), guinea pig FBXO5 (80% identical), pig FBXO5 (76% identical), mouse Fbxo5 (64% identical), rat Fbxo5 (61% identical), tropical clawed frog fbxo5 (35% identical), zebrafish fbxo5 (27% identical), Drosophila melanogaster Rca1 (16% identical). Paralogues in human: FBXO43 (28% identical).
Diseases named in the same sentence as FBXO5 in open-access papers:
FBXO5 is named in the same sentence as 41 diseases in open-access papers, as found by Europe PMC text mining. Sharing a sentence is not in itself a finding about the gene and the disease. The quoted sentences say what the papers report.
breast carcinoma (15 papers, 2018 to 2025). "Furthermore, it was demonstrated that a higher expression level of FBXO5 was significantly associated with a worse prognosis in breast cancer patients." (PMID 36077657, 2022). "In summary, METTL16 promotes breast cancer progression by regulating FBXO5-mediated proliferation and EMT as well as GPX4-mediated ferroptosis resistance, and targeting METTL16 via advanced nanoparticle-based delivery represents a promising therapeutic strategy for TNBC." (PMID 41322419, 2025). "It has been shown that the FBXO5 gene may be a prognostic biomarker in breast cancers, thus providing a potential therapeutic target." (PMID 37550786, 2023). "Second, there are only a few molecular studies on FBXO5 in cancers, including ovarian clear cell carcinoma, esophageal squamous cell carcinoma, breast carcinoma, and hepatocellular carcinoma, and thus the findings on FBXO5 in this research need to be further validated in other tumor types." (PMID 35720327, 2022). "In addition, 5 hub genes, CCNB2, FBXO5, KIF4A, MCM10, and TPX2 were identified and validated to be associated with the progression and worse prognosis of breast cancer." (PMID 30254986, 2018). "Similarly, existing researches also demonstrated that FBXO5 upregulation was critically correlated to the poor prognosis of esophageal squamous cell carcinoma, hepatocellular carcinoma, squamous cell lung carcinoma, and breast cancer." (PMID 35720327, 2022). "According to previous reports, overexpression of FBXO5 produces chromosome instability and mitotic disorder, possibly resulting in the tumorigenesis in ovarian clear cell carcinoma, esophageal squamous cell carcinoma, breast carcinoma, and hepatocellular carcinoma." (PMID 35720327, 2022). "Conversely, FBXO5 overexpression can rescue the tumor-suppressive effects of METTL16 knockdown, confirming the critical role of the METTL16–FBXO5 axis in breast cancer progression." (PMID 41322419, 2025). "FBXO5, also known as early mitosis Inhibitor 1(EMI1), is involved in cell sensitivity to poly ADP-ribose polymerase (PARP) inhibitors by targeting RAD51 degradation in breast cancer." (PMID 36998461, 2023). "Notably, FBXO5 was reported to promote the proliferation of breast cancer cells through PI3K/Akt signaling pathway, leading to a grim prognosis, whereas PI3K inhibitor LY294002 repressed FBXO5 expression and cell proliferative capacity." (PMID 35720327, 2022). "In addition, FBXO5 exhibits a pro-proliferative effect in breast cancer tissues through PI3K/Akt signaling pathway, while PI3K inhibitor can reduce FBXO5 expression and arrest cell growth." (PMID 35720327, 2022).
glioma (4 papers, 2020 to 2025). A benign or malignant brain and spinal cord tumor that arises from glial cells (astrocytes, oligodendrocytes, ependymal cells). "Both MELK and FBXO5 are heavily associated with cancer in general and glioma in particular." (PMID 40378113, 2025). "FBXO5 knockdown can inhibit glioma proliferation, migration and invasion." (PMID 39061113, 2024). "The research have shown that FBXO5, which is regulated by transcription factor ELF1, enhances the proliferation, migration, and invasion of gliomas." (PMID 39061113, 2024).
hepatocellular carcinoma (4 papers, 2019 to 2022). A malignant tumor that arises from hepatocytes. "Studies have also found that FBXO5 is associated with poor prognosis in ovarian cancer, prostate cancer, and hepatocellular carcinoma." (PMID 36004205, 2022). "Furthermore, overexpression of FBXO5 was associated with poor outcome in ovarian cancer, prostate cancer, and hepatocellular carcinoma." (PMID 30341246, 2019). "Moreover, elevated expression of FBXO5 is significantly correlated with an unfavorable prognosis among patients suffering from esophageal squamous cell carcinoma and hepatocellular carcinoma." (PMID 35720327, 2022).
bladder cancer (3 papers, 2012 to 2025). "Four genes (BUB1B, CCNB1, CDC25A and NDC80) were expressed at higher levels in bladder cancer tissues than in normal bladder tissues, but the expression of FBXO5 was lower in bladder cancer than in normal tissues." (PMID 29246203, 2017). "Three SNPs in three genes (FBXO5, SMC3 and SPC24) were associated with significant protective effect on bladder cancer (Ptrend<0.05)." (PMID 22238607, 2012). "However, FBXO5 was negatively regulated by PLK1, which was associated with important clinicopathological characteristics, and FBXO5 siRNA promoted bladder cancer cell proliferation, invasion and migration." (PMID 29246203, 2017). "We performed protein-protein interaction analysis to select five important candidate genes (BUB1B, CCNB1, CDC25A, FBXO5, KIF20A, NDC80) regulated by PLK1 in bladder cancer cells using STRING software." (PMID 29246203, 2017). "To evaluate the significance of the five proteins in bladder cancer, we investigated the relationship between the expression of the five proteins (BUB1B, CCNB1, CDC25A, FBXO5, NDC80) and clinicopathological features." (PMID 29246203, 2017).
cervical cancer (3 papers, 2021 to 2023). A primary or metastatic malignant neoplasm involving the cervix. "FBXO5 (Emi1/FBX5) has been suggested to play crucial roles in the development of HCC, cervical cancer and squamous-cell lung carcinoma in the latest research on bioinformatics analysis." (PMID 33622332, 2021).
triple-negative breast carcinoma (3 papers, 2021 to 2023). An invasive breast carcinoma which is negative for expression of estrogen receptor (ER), progesterone receptor (PR), and human epidermal growth factor receptor 2 (HER2). "A siRNA screen targeting F-box proteins by Michele Pagano's group showed that downregulation of EMI1/FBXO5 in BRCA1-deficient triple-negative breast cancer (TNBC) cells conferred PARPi resistance." (PMID 37609662, 2023).
colon cancer (2 papers, 2023 to 2024). "Intriguingly, gene ontology analysis of FBXO5 co-expressed genes in colon tumor tissues revealed that FBXO5 is associated with cell cycle progression, DNA replication, DNA repair, and spindle pathways, all of which are downregulated during ER stress." (PMID 38212299, 2024). "To understand the mechanism behind FBXO5 down regulation in response to ER stress, we performed a comparative analysis of the 200 co-expressed proteins of FBXO5 in colon cancer and the 489 downregulated proteins in HCT116 cells after thapsigargin treatment." (PMID 38212299, 2024). "Together, these results demonstrate that FBXO5 promotes colon cancer progression in vivo through modulating the expression of CHOP." (PMID 38212299, 2024). "Similar results were obtained when HCT116 cells were treated with tunicamycin and subjected to either FBXO5 knockdown or overexpression, suggesting that FBXO5 plays a role in ER stress-induced apoptosis in colon cancer cells." (PMID 38212299, 2024). "Functionally, we observed significant upregulation of FBXO5 in colon cancer tissues, and its silencing suppresses tumor occurrence in vivo." (PMID 38212299, 2024). "In conclusion, our research highlights FBXO5 as a potential therapeutic target for colon cancer treatment." (PMID 38212299, 2024). "Functional investigation further demonstrated that FBXO5 promotes the survival of colon cancer cells by inhibiting UPR signaling pathways, leading to decreased ER stress and diminished pro-apoptotic activity." (PMID 38212299, 2024). "Furthermore, we demonstrated that FBXO5 plays a crucial role in the progression of colon cancer by promoting the ubiquitination and degradation of RNF183, which leads to the inhibition of ER stress-induced cell apoptosis." (PMID 38212299, 2024). "Interestingly, in colon cancer, FBXO5 is found to be overexpressed and plays a role in preventing ER stress-induced apoptosis via its ability to ubiquitinate and degrade RNF183, a critical regulator of ER stress-induced apoptosis." (PMID 38212299, 2024). "As ER-mediated FBXO5 downregulation plays an important role in ER-induced colon cancer cell apoptosis, we then investigated whether FBXO5 is involved in the oncogenesis of colon cancer." (PMID 38212299, 2024). "Interestingly, GO analysis of 200 co-expressed genes of FBXO5 in TCGA colon tumor tissues revealed a relationship between FBXO5 and cell cycle, DNA replication, DNA repair, and spindle pathways, all of which are down regulated by ER stress." (PMID 38212299, 2024). "Additionally, FBXO5 is found to be upregulated in colon cancer and functions by inhibiting ER stress-induced apoptosis through promoting the ubiquitination degradation of RNF183, thereby contributing to colon cancer progression." (PMID 38212299, 2024). "Furthermore, FBXO5 is significantly upregulated in colon cancer tissues, and knockdown of FBXO5 suppresses tumorigenesis in in vivo nude mice models, indicating that increased FBXO5 expression may contribute to colon cancer tumorigenesis by inhibiting ER stress-induced apoptosis." (PMID 38212299, 2024). "The results revealed that silencing FBXO5 resulted in a decelerated growth of colon cancer cells, while silencing RNF183 effectively reversed the growth arrest induced by FBXO5 silencing." (PMID 38212299, 2024). "Therefore, our study highlights the critical role of the FBXO5/RNF183 axis in ER stress regulation and identifies a potential therapeutic target for colon cancer treatment." (PMID 38212299, 2024). "The validity of these findings was further reinforced by the results showing that three additional UPR inducers, specifically tunicamycin, A23187, and Brefeldin-A, led to significant inhibition of FBXO5 and E2F2 expression in multiple colon cancer cell lines, including HT29, HCT116, and SW480." (PMID 38212299, 2024).
colorectal cancer (2 papers, 2024 to 2025). A primary or metastatic malignant neoplasm that affects the colon or rectum. "Reversal of the apoptosis defects caused by FBXO5 deficiency in colorectal cancer cells can be achieved by knocking down RNF183 in FBXO5-deficient cells." (PMID 38212299, 2024). "To unravel the clinical relevance of FBXO5 in cancer, we further explored the expression of FBXO5 in clinical colorectal cancer tissues." (PMID 38212299, 2024). "Taken together, these finding demonstrates a noteworthy upregulation of FBXO5 in human colorectal cancer (COAD), highlighting its potential as a therapeutic target for cancer prevention." (PMID 38212299, 2024). "Furthermore, validation in clinical colorectal cancer tissues using real-time PCR and western blot corroborated the higher levels of FBXO5 in tumor tissues compared to adjacent normal tissues." (PMID 38212299, 2024). "Importantly, in the GSE62321 cohort, among the 38 quantifiable F-box proteins, FBXO5 was the only significantly upregulated F-box protein in colorectal cancer tissues, further indicating its key role in colorectal cancer." (PMID 38212299, 2024). "Thirdly, we discovered a significant increase in FBXO5 expression in human colorectal cancer." (PMID 38212299, 2024). "However, there have been relatively few reports on the involvement of FBXO5 in colorectal cancer thus far." (PMID 38212299, 2024). "Additionally, analysis of the human protein atlas database revealed an elevated level of FBXO5 protein in colorectal cancer tissues compared to normal samples, as confirmed by immunohistochemical (IHC) staining using anti-FBXO5 antibodies." (PMID 38212299, 2024). "We observed elevated expression of FBXO5 mRNA in COAD tumor tissues in both the TCGA database and the GSE62321 colorectal cancer patient cohort." (PMID 38212299, 2024).
gastric cancer (2 papers, 2022 to 2024). A primary or metastatic malignant neoplasm involving the stomach. "A previous study on the role of CRIP1 can well explain the protective role of FBXO5 in gastric cancer." (PMID 35720327, 2022). "Due to the negative correlation between CRIP1 expression and survival time in gastric cancer patients, FBXO5 may exhibit a potential protective role in the prognosis of gastric cancer through inhibiting the identified function of CRIP1 in this report." (PMID 35720327, 2022). "FBXO5 can block CRIP1-promoted homologous recombination repair by preventing nuclear enrichment of RAD51, thereby restoring chemotherapy sensitivity of gastric cancer cells with high CRIP1 expression." (PMID 35720327, 2022).
glioblastoma (2 papers, 2020 to 2025). The most malignant astrocytic tumor (WHO grade IV). "Testing the robustness of this finding on other BET inhibitors, two additional BET inhibitors (JQ1 and OTX015) were tested on four glioblastoma cell lines and showed consistent down-regulation of the FBXO5 module." (PMID 40378113, 2025).
ovarian clear cell cancer (2 papers, 2018 to 2022). An invasive malignant neoplasm that arises from the ovary and is characterized by a predominance of clear and hobnail malignant epithelial cells. "FBXO5 accumulation is tightly related to mitotic abnormalities including centrosome overduplication and aberrant spindle formation, which cause the emergence of tetraploidy in ovarian clear cell carcinoma." (PMID 35720327, 2022). "In ovarian clear cell carcinoma, FBXO5 accumulation was related to mitotic errors with centrosome overduplication and abnormal spindle formation." (PMID 30254986, 2018).
clear ovarian cell tumors (1 paper, 2021). "Significant overexpression of FBXO5 has been detected in mixed endometrioid/clear ovarian cell tumors but absent in ovarian tumors with mixed serous/clear cell histology." (PMID 33622332, 2021).
endometriosis (1 paper, 2025). The growth of functional endometrial tissue in anatomic sites outside the uterine body. "Our study has identified eight potential mitosis hub genes (KIF4A, BUB1B, NEK2, FBXO5, KIF11, CENPE, CCNA2, and NCAPG) that exhibit excellent diagnostic properties for endometriosis." (PMID 40772274, 2025). "Then, we identified 11 potential mitosis-related downregulated hub genes, among which eight genes (KIF4A, BUB1B, NEK2, FBXO5, KIF11, CENPE, CCNA2, and NCAPG) showed good diagnostic properties of endometriosis and two genes (CCNA2, CENPE) were closely related to infertile endometriosis." (PMID 40772274, 2025). "We used the GSE25628 dataset to detect the expression of selected target genes, and the results showed that the differential expression of eight MRHGs (KIF4A, BUB1B, NEK2, FBXO5, KIF11, CENPE, CCNA2, and NCAPG) between control and endometriosis patients was consistent with predictions." (PMID 40772274, 2025).
Epstein-Barr virus infection (1 paper, 2022). An infection that is caused by Epstein-Barr virus. "Of note, FBXO5 was found to be critically involved in immune-associated tumorigenic virus infectious diseases, including hepatitis B, hepatitis C, human T-cell leukemia virus 1 infection, and Epstein-Barr virus infection." (PMID 35720327, 2022).
lung carcinoma (1 paper, 2021). "Finally, FBXO5 is partially methylated in bladder and lung cancers, but is predominantly hypomethylated in all remaining cancer types." (PMID 35008511, 2021).
Pan (1 paper, 2022). "Pan-cancer survival analysis showed that FBXO5 promoter methylation levels were obviously correlated with better OS in patients diagnosed as ACC, KIRP, LGG, MESO, and SARC, which was opposite in KIRC and LAML patients." (PMID 35720327, 2022).
stomach adenocarcinoma (1 paper, 2022). "Notably, highly expressed FBXO5 in STAD (stomach adenocarcinoma) was a protective factor for DFI and PFI survival, and this was different from most cancers in which increased FBXO5 acted as an unfavorable prognostic factor, implying that FBXO5 may have specific functions in STAD." (PMID 35720327, 2022).